SEC31B (SEC31 homolog B, COPII component)
Description:
As a component of the coat protein complex II (COPII), may function in vesicle budding and cargo export from the endoplasmic reticulum.
Synonyms: SEC31L2; SEC31B-1; DKFZP434M183
Tractability: Antibody: UniProt places it where antibodies can reach, with high confidence. PROTAC: UniProt records ubiquitination sites on it; ubiquitination databases record sites on it.
Gene: Protein-coding gene on chromosome 10 (100,486,639 to 100,519,864, reverse strand). Ensembl gene ENSG00000075826.
Subcellular location: Cytoplasm; Cytoplasmic vesicle, COPII-coated vesicle membrane; Endoplasmic reticulum membrane
Subcellular location (Human Protein Atlas): Cytosol; Nucleoplasm; Vesicles
Pathways (Reactome):
Vesicle-mediated transport: COPII-mediated vesicle transport
Gene Ontology:
Molecular function: structural molecule activity
Biological process: COPII-coated vesicle cargo loading; endoplasmic reticulum organization; positive regulation of ER to Golgi vesicle-mediated transport; endoplasmic reticulum to Golgi vesicle-mediated transport
Cellular component: cytosol; vesicle coat; COPII vesicle coat; endoplasmic reticulum; endoplasmic reticulum exit site; cytoplasm; endoplasmic reticulum membrane; ER to Golgi transport vesicle membrane
Genetic constraint (gnomAD): Loss-of-function variants: 113 observed, 139.56 expected, observed/expected ratio (o/e) 0.81, 90% interval 0.69 to 0.95. The upper end of that interval is the gene's LOEUF score, 0.95, which puts it in group 4 of 6, group 1 being the genes least tolerant of losing a copy. Missense variants: 1,296 observed, 1,468 expected, observed/expected ratio (o/e) 0.88, 90% interval 0.84 to 0.92. Synonymous variants: 508 observed, 569.73 expected, observed/expected ratio (o/e) 0.89, 90% interval 0.83 to 0.96.
Homologues: Orthologues: chimpanzee SEC31B (96% identical), macaque SEC31B (93% identical), dog SEC31B (83% identical), pig SEC31B (82% identical), mouse Sec31b (78% identical), rat Sec31b (78% identical), rabbit SEC31B (76% identical), guinea pig SEC31B (75% identical), tropical clawed frog sec31b (55% identical), zebrafish sec31b (48% identical), Drosophila melanogaster Sec31 (33% identical), Caenorhabditis elegans sec-31 (21% identical). Paralogues in human: SEC31A (49% identical).
Diseases named in the same sentence as SEC31B in open-access papers:
SEC31B is named in the same sentence as 4 diseases in open-access papers, as found by Europe PMC text mining. Sharing a sentence is not in itself a finding about the gene and the disease. The quoted sentences say what the papers report.
diarrheal disease (1 paper, 2022). The condition of having at least three loose or liquid bowel movements each day. "Our study reports five such proteins, RAPH1, GCNT7, ADAMTS1, GLI1, and SEC31B, which are strong binding partners of other significant proteins and could thus be targeted for the discovery of a common medication system against diarrheal disease." (PMID 36473896, 2022).
retinitis pigmentosa (1 paper, 2021). Retinitis pigmentosa (RP) is an inherited retinal dystrophy leading to progressive loss of the photoreceptors and retinal pigment epithelium and resulting in blindness usually after several decades. "Strikingly, eight of the 67 exclusive candidates are associated with retinitis pigmentosa (human orthologues in parentheses): Gnat1 (GNAT1), Rom1a and Rom1b (ROM1), Kfharr-r2 (SAG, ARRESTIN, RP47), Rgra (RGR, RP44), Tbl2 (TBL2), Sec31b (SEC31B) and Glyr1 (GLYR1)." (PMID 34106226, 2021).
tumor (1 paper, 2023). "SEC31B is crucial for the growth of the pollen wall, although its function in tumor cells is uncertain." (PMID 37064125, 2023).
SEC31B also shares sentences with these, for which no sentence is quoted: cancer (1 paper).